ELANE (elastase, neutrophil expressed)
Diseases named in the same sentence as ELANE in open-access papers (continued):
Sharing a sentence is not in itself a finding about the gene and the disease.
congenital neutropenia (51 papers, 2004 to 2025). "Mutations in the ELANE gene, which encodes neutrophil elastase, are known to cause cyclic neutropenia (CyN) and severe congenital neutropenia (SCN)." (PMID 40787460, 2025). "For instance, mutations in ELANE, which encodes neutrophil elastase, lead to severe congenital neutropenia (SCN) through the accumulation of misfolded protein and ER stress, resulting in increased cell death of neutrophil precursors." (PMID 40964614, 2025). "Autosomal dominant mutations in ELANE (elastase, neutrophil expressed) cause severe congenital neutropenia (CN) and cyclic neutropenia (CyN)." (PMID 41438873, 2025). "Several pathophysiological mechanisms have been proposed to explain congenital neutropenia associated with ELANE mutations." (PMID 41477439, 2025). "Germline heterozygous point mutations in the gene ELANE, which encodes neutrophil elastase (NE), are the most frequent cause of severe congenital neutropenia (SCN)." (PMID 39560992, 2024). "Neutrophil elastase (ELANE) mutations are the most common cause of cyclic (CyN) and congenital neutropenia (SCN), two autosomal dominant disorders causing recurrent infections due to impaired neutrophil production." (PMID 39867870, 2024). "Single-nucleotide polymorphisms in the ELANE (Elastase, Neutrophil Expressed) gene are associated with severe congenital neutropenia, while the ELANE gene provides instructions for making a protein called neutrophil elastase." (PMID 35571273, 2022). "Heterozygous mutations in ELANE, the gene for neutrophil elastase, cause cyclic and congenital neutropenia through the programed cell death of neutrophil progenitors in the bone marrow." (PMID 36052149, 2022). "We acknowledge that we have examined only 3 of the more than 100 different ELANE mutations associated with cyclic and congenital neutropenia." (PMID 36052149, 2022). "Mutations in ELANE, the gene for neutrophil elastase (NE), are the most common cause of cyclic and severe congenital neutropenia." (PMID 36052149, 2022). "This research sheds light on how ELANE failure upon mutation results in disease progression, including congenital neutropenia, and validation of these novel predicted nsSNPs is required through the wet lab." (PMID 35571273, 2022). "Mutations of neutrophil elastase gene (ELANE) are ones of the most commonly observed in patients suffering from congenital neutropenia." (PMID 33968054, 2021). "Patients with ELANE variants and severe congenital neutropenia (SCN) commonly develop oral complications." (PMID 34580954, 2021). "Vandenberghe and Beel reported that ELANE mutation associated with severe congenital neutropenia increased the risk of AML." (PMID 33299888, 2020). "Severe periodontitis has been described in patients with Severe Congenital Neutropenia due to mutations in the neutrophil elastase (NE) ELA2/ELANE or the HAX1 gene (hematopoietic cell-specific Lyn substrate) 1-associated gene X1." (PMID 32575367, 2020). "This group includes congenital neutropenia caused by mutations in ELANE, GFI1, HAX1, WAS (X-linked neutropenia), CSF3R, and SRP54 genes." (PMID 31709206, 2019). "We asked the question to what extent the composition of the proteome differed among patients with severe congenital neutropenia because of mutations in ELANE and healthy individuals." (PMID 30630937, 2019). "Severe congenital neutropenia 1 (SCN1) caused by ELANE mutations is a rare disease characterized by very low numbers of circulating neutrophils." (PMID 31176364, 2019). "More than 50% of patients with severe congenital neutropenias (SCNs) and nearly all patients with cyclic neutropenia have autosomal dominant (AD) monoallelic mutations in ELANE, the gene that encodes neutrophil elastase." (PMID 28894446, 2017). "Mutations in ELANE are found in nearly 100% of individuals with typical features of CN and in 38 - 80% of individuals with congenital neutropenia." (PMID 25880377, 2015).
congenital neutropenia (continued). "Soon after the discovery of their involvement in cyclic neutropenia, ELANE mutations (about 50 listed to date) were also identified in patients with severe congenital neutropenia." (PMID 21595885, 2011). "Here the clinical picture is very similar to that of severe congenital neutropenia due to ELANE mutations, but this disorder is entirely unresponsive to G-CSF, even at doses up to 100 μg/kg per day." (PMID 21595885, 2011). "The patients with severe congenital neutropenia caused by mutations in the gene coding neutrophil elastase (ELANE) and especially cyclic neutropenia (CyN) present recurrent periodontitis and fever episodes, whose severity cannot be fully explained as an infectious complication." (PMID 37350970, 2023). "Clinical features of severe congenital neutropenia caused by ELANE gene mutation." (PMID 36343040, 2022). "As there is a wide spectrum of ELANE mutations, over the years of research, other hypotheses for the pathogenesis of congenital neutropenia have been proposed." (PMID 33968054, 2021). "Moreover, mutations in 5’UTR and deep intronic region of ELANE gene have been reported to be associated with severe congenital neutropenia." (PMID 32555368, 2020). "Mutations in the ELANE gene cause congenital neutropenia, clinically differentiated into two forms: cyclic neutropenia (CyN) and SCN, depending on whether the reduction in neutrophil granulocytes in the peripheral blood occurs intermittently or persists continuously." (PMID 41477439, 2025). "Previous studies have primarily focused on the relationship between ELANE gene mutations and severe congenital neutropenia (SCN) as well as their progression to myelodysplastic syndromes/acute myeloid leukemia (MDS/AML)." (PMID 40073065, 2025). "Severe congenital neutropenia (SCN) is caused by germline mutations, most commonly in ELANE, impacting neutrophil maturation and leading to high risk of life-threatening infections." (PMID 38469307, 2024). "Severe congenital neutropenia (SCN) is frequently associated with dominant point mutations in ELANE, the gene encoding neutrophil elastase (NE)." (PMID 39560992, 2024). "Severe congenital neutropenia (SCN) is a rare inherited disease that impairs neutrophil maturation and is frequently caused by autosomal-dominant mutations in the ELANE gene." (PMID 38786024, 2024). "The most common mutation causing severe congenital neutropenia (SCN) and cyclic neutropenia (CyN) is the ELANE gene." (PMID 37993852, 2023). "Interestingly, the same ELANE mutation present within the family might be associated with a clinical phenotype of CyN and severe congenital neutropenia suggesting that also other factors affect the clinical manifestation of the disease." (PMID 33968054, 2021). "Inherited heterozygous point mutations in the ELANE gene, which encodes neutrophil elastase (NE), activates severe congenital neutropenia (SCN)." (PMID 27304053, 2016). "Shortly afterwards the same team found that many patients with severe congenital neutropenia also had mutations of the ELANE gene This pointed to a continuum between severe congenital neutropenia and cyclic neutropenia, and showed that both could be considered "congenital"." (PMID 21595885, 2011). "Antenatal diagnosis has already been performed for the following disorders: severe congenital neutropenia with pathogenic ELANE mutations, Shwachman-Diamond syndrome, WHIM syndrome and glycogen storage disease type Ib and may be offered for many other entities, such as HAX1 and G6PC3." (PMID 21595885, 2011). "Notably, the ELANE gene mutation, linked with severe congenital neutropenia (SCN) and cyclic neutropenia (CN), was associated with early-onset aggressive periodontitis and horizontal bone loss in five studies." (PMID 40932944, 2025).
congenital neutropenia (continued). "Based on the results obtained, 102 patients belonging to 80 different families were diagnosed with severe congenital neutropenia (SCN) and neutropenia-related syndromes, the majority (43%) of whom harbored variants in the ELANE gene, including 12 novel ones." (PMID 41383606, 2025). "In severe congenital neutropenia (SCN), mutations such as ELANE p.Ala79del (c.234_236del) and p.Val197GlufsTer18 (c.589_590insAGGCCGGC) disrupt neutrophil elastase function, while a de novo SEC61A1 missense mutation (c.A275G; p.Q92R) further expands the genetic heterogeneity of SCN." (PMID 41141324, 2025). "The ELANE gene should be tested in all cases of “unexplained-idiopathic” congenital neutropenia." (PMID 38921186, 2024). "About half the forms of congenital neutropenia with no extra-hematopoetic manifestations and normal adaptive immunity are due to neutrophil elastase (ELANE) mutations." (PMID 21595885, 2011). "Mice with no ELANE gene expression or carrying mutations associated with severe congenital neutropenia in humans are not neutropenic." (PMID 21595885, 2011). "CSF3R truncation mutations are also prevalent in patients with severe congenital neutropenia (SCN), a condition with heterogenous basis often related to mutations in the ELANE gene encoding neutrophil elastase." (PMID 35200567, 2022). "The risk of leukemia is increased with some severe congenital neutropenia (ELANE, HAX1, and WASP) but not increased with the ELANE mutation that causes cyclic neutropenia." (PMID 35887984, 2022). "Indeed, mutation of the only transcription factor (GFI1) known to be involved in congenital neutropenia may not directly affect the transcription process but interfere with interaction with ELANE protein." (PMID 21595885, 2011).
cystic fibrosis (48 papers, 2009 to 2025). Autosomal recessive disorder caused by pathogenic variants in the CFTR gene (cystic fibrosis transmembrane conductance regulator), which encodes a chloride and bicarbonate channel expressed in epithelial cells, and follow the diagnosis criteria. "Recent research found strong evidence that the ELANE gene mainly enhances proinflammatory cytokines and can subsequently cause epithelial cell injuries in cystic fibrosis patients." (PMID 35891565, 2022). "ELANE which encodes neutrophil elastase, together with matrix metalloproteinase 12 (MMP12), has been reported in the development cystic fibrosis in lungs." (PMID 30245726, 2018).
asthma (30 papers, 2010 to 2025). "Most DEGs of this term, including DEFA3, DEFA4, ELANE, and LTF, encode antimicrobial peptides in neutrophils, indicating that the upregulated antimicrobial immune response in the AR-asthma group is mainly mediated by neutrophils." (PMID 36569909, 2022). "Outside the weed pollen season, the expression levels of LTF, PF4, and ELANE in the AR-asthma group were significantly higher than those in the AR group." (PMID 36569909, 2022). "Additionally, platelet factor 4 has been found to induce airway hyper-responsiveness in an asthma model.However, studies on the comparison of the expression levels of ELANE or PF4 between patients with AR and those with asthma are rare." (PMID 36569909, 2022). "In the present study, the AR-asthma group showed upregulated ELANE and PF4 expression compared to the AR group in the transcriptomic analysis, suggesting that increased elastase and platelet factor 4 may contribute to the development of allergic asthma from AR." (PMID 36569909, 2022). "It has been reported that ELANE and PF4 are closely related to the pathogenesis of asthma." (PMID 36569909, 2022). "The results of the qPCR showed that during the weed pollen season, the expression levels of ELANE and LTF in the AR-asthma group were significantly higher than those in the AR group, whereas the expression levels of PF4 in the two groups were not significantly different." (PMID 36569909, 2022).
acute respiratory distress syndrome (28 papers, 2010 to 2025). Progressive and life-threatening pulmonary distress in the absence of an underlying pulmonary condition, usually following major trauma or surgery. "Neutrophil Elastase (ELANE) is an inflammatory mediator of neutrophils that is predictive of development of acute lung injury (ALI) or acute respiratory distress syndrome (ARDS), however its role in influenza infections is debatable." (PMID 34691044, 2021).
breast carcinoma (26 papers, 1994 to 2025). "These EVs were loaded with hiltonol and neutrophil elastase (ELANE), two drugs targeted at breast cancer, using lentiviral transfection." (PMID 38435823, 2024). "In the present study, we developed an in situ DC vaccine (HELA-Exos) by using engineered breast cancer-derived exosomes to codeliver the ICD inducers ELANE and Hiltonol for the treatment of breast cancer." (PMID 35148751, 2022). "Herein, we developed and optimized a formulation of target-specific exosomes loaded with Hiltonol (TLR3 agonist) and the ICD inducer human neutrophil elastase (ELANE) to form an in situ DC vaccine for breast cancer treatment." (PMID 35148751, 2022). "One study loaded an ICD inducer, human neutrophil elastase (ELANE), and a TLR3 agonist Hiltonol onto breast cancer-derived Tu-sEVs to form an in situ vaccine (HELA-sEVs)." (PMID 37681880, 2023). "We loaded the immunogenic cell death (ICD) inducers human neutrophil elastase (ELANE) and Hiltonol (TLR3 agonist) into α-lactalbumin (α-LA)-engineered breast cancer-derived exosomes to form an in situ DC vaccine (HELA-Exos)." (PMID 35148751, 2022). "In another study, researchers made genetically engineered breast cancer cell-derived exosomes that overexpress α-lactalbumin (α-LA) and loaded them with immunogenic cell death (ICD) inducers, ELANE (catalytically active neutrophil elastase) and Hiltonol (TLR3 agonist), simultaneously." (PMID 38793770, 2024). "In another recent study, α-lactalbumin (α-LA)-engineered breast cancer cell-derived exosomes were loaded with immunogenic cell death (ICD) inducers Hiltonol (a Toll-like receptor agonist) and human neutrophil elastase (ELANE) to form an in situ DC vaccine (HELA-Exos)." (PMID 37345176, 2023).
Cyclic neutropenia (26 papers, 2011 to 2026). "Park and co-authors published the case describing a patient with the variant in the ELANE gene presenting episodes of cyclic neutropenia." (PMID 39975544, 2025). "Cyclic neutropenia is a rare autosomal dominant disorder caused by specific mutations in the ELANE gene." (PMID 40418265, 2025). "ELANE gene is present in a gene cluster on chromosome 19 and is associated, apart from congenital neutropenia syndromes, with cyclic neutropenia." (PMID 38921186, 2024). "Cyclic neutropenia (CN) is a rare haematologic disorder that is associated with mutations of the ELANE gene." (PMID 37138249, 2023). "We report a 31-month-old girl with congenital cyclic neutropenia with a novel mutation in the ELANE gene who developed an acute necrotizing soft-tissue infection on her left axillary legion." (PMID 25880377, 2015). "In 1999, M. Horwitz, analyzing 13 pedigrees of patients with cyclic neutropenia, identified mutations in the neutrophil elastase (ELANE) gene." (PMID 21595885, 2011). "Cyclic neutropenia, or cyclic agranulocytosis, is a rare hematological disorder (1:1,000,000 in the general population) with an autosomal-dominant pattern of transmission, in which mutations occur in the gene for neutrophil elastase (ELA2 or ELANE)." (PMID 38921186, 2024). "The genetic basis of the disease has been evaluated and established in molecular biology, showing that cyclic neutropenia is inherited as an autosomal-dominant mutation of the gene for neutrophil elastase (ELANE) with full penetrance but different severities of manifestation." (PMID 37834967, 2023). "Interestingly, patients with cyclic neutropenia (CyN) also harbor mutations within the ELANE gene, even in the same nucleotide position." (PMID 30891028, 2019). "Among them, ELANE, which encodes neutrophil elastase, is the most common gene mutation that causes SCN and cyclic neutropenia (CyN)." (PMID 41226891, 2025). "Mutations in the neutrophil elastase (ELANE) gene are frequently found in SCN and cyclic neutropenia." (PMID 27942017, 2016). "In congenital neutropenic syndromes, such as SCN and cyclic neutropenia, mutations in genes such as ELANE (encoding neutrophil elastase), HAX1, and GFI1 lead to defective neutrophil maturation, resulting in a near-complete absence of mature neutrophils in the circulation." (PMID 40418265, 2025).
Insulin resistance (25 papers, 2013 to 2025). Increased resistance towards insulin, that is, diminished effectiveness of insulin in reducing blood glucose levels. "The current study revealed that several cytokines—including RETN, CTSG, and ELANE, which can promote vascular damage and insulin resistance—were upregulated in the DM R+ group." (PMID 40641746, 2025). "Also, MMP9, ELANE, NOTCH1, with fewer connected targets, have all been proven to have important regulatory effects in reducing liver lipid accumulation, inflammatory responses, fibrosis, and improving insulin resistance." (PMID 36451177, 2022).
lung carcinoma (25 papers, 2004 to 2025). "Furthermore, evidence from lung cancer models indicates that ELANE promotes M2 macrophage polarization via PTEN downregulation, thus fostering a tumor-promoting microenvironment that enhances proliferation, migration, and invasion." (PMID 40748972, 2025). "In contrast, no apparent clustering of high ELANE expressers was observed in the unsupervised hierarchical cluster analysis of the lung cancer specimens." (PMID 38219859, 2024).
periodontitis (23 papers, 2012 to 2025). An acute or chronic inflammatory process that affects the tissues that surround and support the teeth. "The inability of patients with PLS and most of those with ELANE mutations to form NETs is concomitant with aggressive periodontitis." (PMID 29123528, 2017). "Similarly, mutations in ELANE gene encoding NE are associated with aggressive periodontitis in the majority of patients with such mutations." (PMID 29123528, 2017). "Moreover, patients with Papillon-Lefèvre syndrome (PLS), characterized by mutations that inactivate Cathepsin C, a cysteine protease that processes ELANE into its active state, develop severe periodontitis." (PMID 32243431, 2020). "Additionally, the ELANE rs17223045C/T has been assessed in other infectious diseases, such as initial periodontitis in adolescents, and has not been associated to this pathology." (PMID 38226800, 2024).
Obesity (21 papers, 2020 to 2025). Accumulation of substantial excess body fat. "Evidence in mice has established a role for neutrophil elastase (NE; ELANE) in obesity-associated metabolic dysregulation." (PMID 39788946, 2025). "In the PPI network constructed based on these genes, LCN2, ELANE, and MMP8 processed the most nodes, indicating their key roles in the obesity-related immune network." (PMID 39609876, 2024). "Many of the upregulated immature neutrophil genes (e.g., OLFM4, DEFA1, ELANE, CEACAM6, CEACAM8, CTSG) have been found to be differentially expressed in persons with obesity and type 2 diabetes, both common comorbidities with psychotic disorders." (PMID 37147304, 2023). "CNTNAP2, GLI2, DPT (dermatopontin), AEBP1, ITIH5, CXCL11, GDNF (glial cell derived neurotrophic factor), MCHR1, FLT3, ELANE (elastase, neutrophil expressed), OSMR (oncostatin M receptor) and IL15RA are involved in development of obesity, but these genes might be key for progression of HF." (PMID 34218797, 2021). "Therefore, in this study, the elevated expression of upregulated DEGs enriched in serine metabolism, such as ELANE, CTSG, and MMP8, could result in increased serine hydrolysis and a subsequent reduction in serine levels within the body, thereby contributing to the onset and development of obesity." (PMID 39609876, 2024).